EPHA5 (EPH receptor A5)
Description:
Receptor tyrosine kinase which binds promiscuously GPI-anchored ephrin-A family ligands residing on adjacent cells, leading to contact-dependent bidirectional signaling into neighboring cells. The signaling pathway downstream of the receptor is referred to as forward signaling while the signaling pathway downstream of the ephrin ligand is referred to as reverse signaling. Among GPI-anchored ephrin-A ligands, EFNA5 most probably constitutes the cognate/functional ligand for EPHA5. Functions as an axon guidance molecule during development and may be involved in the development of the retinotectal, entorhino-hippocampal and hippocamposeptal pathways. Together with EFNA5 plays also a role in synaptic plasticity in adult brain through regulation of synaptogenesis. In addition to its function in the nervous system, the interaction of EPHA5 with EFNA5 mediates communication between pancreatic islet cells to regulate glucose-stimulated insulin secretion (By similarity).
Synonyms: EHK-1; EK7; hEK7; EHK1; TYRO4; CEK7
Tractability: Small molecule: an approved drug acts on it; a high-quality ligand is known; it has a binding pocket of medium quality; it belongs to a druggable protein family. Antibody: UniProt places it where antibodies can reach, with high confidence; its Gene Ontology location is reachable by antibodies, with high confidence; UniProt predicts a signal peptide or a membrane-spanning region. PROTAC: ubiquitination databases record sites on it; its protein half-life has been measured; a small molecule that binds it is known.
Target class: Tyrosine protein kinase Eph family; Protein Kinase; TK protein kinase group; Kinase; Enzyme
Safety:
Unwanted effects reported when the protein is acted on. In parentheses: how it was acted on, where the effect was seen, and who reports it.
peripheral neuropathy (source: ClinPGx)
Gene: Protein-coding gene on chromosome 4 (65,319,563 to 65,670,495, reverse strand). Ensembl gene ENSG00000145242.
Subcellular location: Cell membrane; Cell projection, axon; Cell projection, dendrite
Subcellular location (Human Protein Atlas): Golgi apparatus; Plasma membrane; Vesicles
Pathways (Reactome):
Developmental Biology: EPH-Ephrin signaling; EPH-ephrin mediated repulsion of cells; EPHA-mediated growth cone collapse
Gene Ontology:
Molecular function: ephrin receptor activity; protein binding; GPI-linked ephrin receptor activity; transmembrane-ephrin receptor activity; ATP binding; protein kinase activity; protein tyrosine kinase activity; transmembrane receptor protein tyrosine kinase activity
Biological process: ephrin receptor signaling pathway; neuron development; axon guidance; axonal fasciculation; hippocampus development; negative regulation of insulin secretion involved in cellular response to glucose stimulus; cell surface receptor protein tyrosine kinase signaling pathway
Cellular component: dendrite; external side of plasma membrane; neuronal cell body; perinuclear region of cytoplasm; plasma membrane; rough endoplasmic reticulum; axon; insulin-responsive compartment; neuron projection; membrane
Genetic constraint (gnomAD): Loss-of-function variants: 55 observed, 96.81 expected, observed/expected ratio (o/e) 0.57, 90% interval 0.46 to 0.71. The upper end of that interval is the gene's LOEUF score, 0.71, which puts it in group 2 of 6, group 1 being the genes least tolerant of losing a copy. Missense variants: 1,178 observed, 1,246.8 expected, observed/expected ratio (o/e) 0.94, 90% interval 0.9 to 0.99. Synonymous variants: 501 observed, 437.92 expected, observed/expected ratio (o/e) 1.14, 90% interval 1.06 to 1.23.
Homologues: Orthologues: chimpanzee EPHA5 (99% identical), macaque EPHA5 (99% identical), pig EPHA5 (98% identical), dog EPHA5 (97% identical), rat Epha5 (97% identical), mouse Epha5 (96% identical), tropical clawed frog epha5 (84% identical). Paralogues in human: EPHA3 (65% identical), EPHA4 (63% identical), EPHA7 (62% identical), EPHA6 (60% identical), EPHA8 (57% identical), EPHB2 (56% identical), EPHB1 (55% identical), EPHB3 (55% identical), EPHA2 (51% identical), EPHB4 (47% identical), EPHA10 (46% identical), EPHA1 (41% identical), and 41 more.
Diseases named in the same sentence as EPHA5 in open-access papers:
EPHA5 is named in the same sentence as 84 diseases in open-access papers, as found by Europe PMC text mining. Sharing a sentence is not in itself a finding about the gene and the disease. The quoted sentences say what the papers report.
breast cancer (16 papers, 2011 to 2025). A primary or metastatic malignant neoplasm involving the breast. "The low expression of EphA5 was associated with lymph node metastasis of breast cancer, colorectal cancer and gastric cancer, indicating poor prognosis in colorectal carcinoma and ovarian cancer." (PMID 31956298, 2020). "Furthermore, decreased expression of the EPHA5 gene is seen after hypermethylation, which was associated with a poor breast cancer prognosis." (PMID 36164608, 2022). "Furthermore, the report found that loss of EphA5 resulted in higher expression of cancer stem cell (CSC) markers in HER2-positive breast cancer cells, including CD44+/CD24-/low, NANOG, CD133+." (PMID 31956298, 2020). "More precisely, EPHA5 is implicated in mediating developmental events and plays a critical role in the regulation of carcinogenesis, since it has been demonstrated to be a promoter of methylation in breast cancer." (PMID 27895661, 2016). "However, other studies have shown that the EphA5 promoter is hypermethylated in colorectal and breast cancer leading to decreased receptor expression, and that EphA5 expression is associated with tumor dormancy." (PMID 24086308, 2013). "The study also showed that downregulation of EPHA5 in HER2+ breast cancer cells induced trastuzumab resistance, whereas forced overexpression led to increased sensitivity." (PMID 36291900, 2022). "A recent study reported that in HER2-positive breast cancers treated with trastuzumab EphA5 was involved in the cell cycle and apoptosis." (PMID 31956298, 2020). "Recently several groups demonstrated EphA5 promoter methylation in breast cancer, colorectal cancer and acute lymphoblastic leukemia, implying that the hypermethylation of EphA5 paly an important role in cancer progress." (PMID 25609195, 2015). "EphA5, a member of Eph receptors, has been implicated in various biological activities, including tumorigenesis and progression of different cancers, radioresistance in lung cancer and sensitivity to trastuzumab in HER2-positive breast cancer." (PMID 31956298, 2020). "EphA5 gene silenced by methylation has been demonstrated in breast cancer, prostate cancer, and colorectal cancer, implying that the hypermethylation of EphA5 might be of great importance during tumorigenesis and progression in cancer." (PMID 27887627, 2016). "Moreover, the downregulation of EphA5 expression was also observed in other advanced tumors, including colorectal cancer, acute lymphocytic leukemia, and breast cancer." (PMID 25609195, 2015). "While we did not observe any significant associations between EphA5 and clinical outcome, an independent profiling study reported reduced ephA5 expression in human breast cancer samples relative to normal human breast tissue, likely due to aberrant promoter methylation." (PMID 21935409, 2011). "Low EPHA5 is associated with high tumor grade, lymph node metastasis and PgR negative status in breast cancer, indicating that down regulation of EPHA5 could be an important step in tumor progression." (PMID 26870995, 2016). "In the UALCAN database, the mRNA expression of EPHA1, EPHA10, EFNA1, EFNA3, and EFNA4 was significantly higher, whereas that of EPHA2, EPHA4, EPHA5, and EFNA5 was significantly lower in breast cancer tissues than in paracancerous tissues." (PMID 33977106, 2021). "RNA interference-mediated suppression of five candidate genes (DDX10, SKA3, EPHA5, CLTC and TNIK) led to inhibition of breast cancer cell growth." (PMID 23496902, 2013). "hRNase 1 induced phosphorylation of EphA4, but not of EphA3 or EphA5, and activation of phospholipase C-γ (PLCγ), a downstream signaling molecule of EphA430, in BT-549 basal-like breast cancer cells." (PMID 33986289, 2021).
breast cancer (continued). "Using whole genome mate pair sequencing and RNA interference assays, we have discovered a number of novel gene rearrangements in breast cancer genomes and identified DDX10, SKA3, EPHA5, CLTC and TNIK as potential cancer genes with impact on the growth and proliferation of breast cancer cells." (PMID 23496902, 2013).
prostate carcinoma (10 papers, 2015 to 2025). A carcinoma that arises from epithelial cells of the prostate gland. "Previous reports have shown that EPHA5 methylation is associated with a poor prostate cancer prognosis." (PMID 36164608, 2022). "Downregulation or loss of EphA5 mRNA or protein expression was detected in 28 of 45 (62.2%) prostate carcinomas, 2 of 39 (5.1%) hyperplasias, and all 6 prostate cancer cell lines." (PMID 25609195, 2015). "In summary, we have established that loss of EphA5 expression in prostate cancer may be due to methylation of CpG sites within the EphA5 promoter." (PMID 25609195, 2015). "The downregulation of EphA5 was also associated with increased Gleason score in prostate cancer." (PMID 25609195, 2015). "The genes ITGBL1, DSC3, COL4A6, ANGPT1, ARMCX1, MICAL2, and EPHA5 have been recognized as pivotal genes that substantially affect the microenvironment of prostate cancer." (PMID 40943497, 2025). "Low EphA5 expression is associated with a higher grade on the TNM Classification of Malignant Tumors and Gleason scale—two basic prognostic factors in prostate cancer." (PMID 33007931, 2020). "While EphA1 abundance was decreased in prostate cancer cell lines, EphA2, EphA5, EphA6, EphA7, EphA8, and EphA10 levels were elevated in some of the prostate cancer cell lines as compared to the normal prostate cell line." (PMID 29682554, 2018). "The EphA receptors that are decreased or lost in prostate cancer include EphA5 in patients with a Gleason score of 8, EphA6 in LNCaP-19 cell line, and EphA7 in prostate tumor specimens." (PMID 29682554, 2018). "Prostate cancer cells invasion and migration were significantly suppressed by ectopic expression of EphA5 in vitro." (PMID 25609195, 2015). "Among the 23 paired prostate carcinoma specimens, the hypermethylation of EphA5 was detected in 69.6% (16/23) prostate carcinoma tissues." (PMID 25609195, 2015). "Consistent with previous studies, the downregulation of EphA5 expression was also observed in 28 of 45 (62.2%) prostate cancer tissues with various histological stages and in all 6 PCa cell lines." (PMID 25609195, 2015). "To determine the potential mechanism of EphA5 downregulation in prostate cancer, we analyzed the EphA5 gene 5′ regulatory region." (PMID 25609195, 2015). "A significant reduction of EphA5 transcripts in high-grade prostate cancer tissue was shown using a transcriptomic analysis, compared to the low-grade prostate cancer tissue." (PMID 25609195, 2015). "Of these 32 methylated prostate cancer samples, EphA5 expression was markedly downregulated in 25 samples." (PMID 25609195, 2015). "A significant correlation was observed between the downregulation of EphA5 expression and EphA5 methylation in prostate cancer." (PMID 25609195, 2015). "The evidence suggests a potentially suppressive role of EphA5 transcripts in prostate carcinoma progression." (PMID 25609195, 2015). "EphA5 mRNA expression was downregulated in 28 of 45 (62.2%) prostate cancer samples and in 2 of 39 (5.1%) BPH samples." (PMID 25609195, 2015). "The EphA5 gene was frequently silenced by an epigenetic alteration, namely DNA methylation in prostate cancer cell lines and tissues." (PMID 25609195, 2015). "The frequency of EphA5 promoter methylation was significantly higher in prostate cancer samples (32 of 45, 71.1%) than in BPH tissue samples (5 of 39, 12.8%; p < 0.01) and paired noncancerous tissues (2 of 23, 8.7%; p < 0.01)." (PMID 25609195, 2015). "Following the treatment of 6 prostate cancer cell lines with 5-aza-2′-deoxycytidine, the levels of EphA5 mRNA were significantly increased." (PMID 25609195, 2015). "Among 23 paired prostate carcinoma tissues, 16 tumor samples exhibited the hypermethylation of EphA5, and 15 of these 16 specimens (93.8%) shown the downregulation of EphA5 expression than that of their respectively matched noncancerous samples." (PMID 25609195, 2015).
prostate carcinoma (continued). "The role of EphA5 in prostate cancer cell migration and invasion was examined by wound healing and transwell assay." (PMID 25609195, 2015). "Our data indicate that EphA5 is a potential prognostic biomarker and a useful molecular therapeutic target to attenuate prostate cancer progression." (PMID 25609195, 2015). "Methylation of the EphA5 promoter region was present in 32 of 45 (71.1%) carcinoma samples, 3 of 39 (7.7%) hyperplasias, and the 6 prostate cancer cell lines." (PMID 25609195, 2015). "However, EphA5 and EphB4 are present at both the plasma membrane and the cytoplasm of lung cancer and prostate cancer cells, respectively." (PMID 36214254, 2022). "Similarly, EphA5 has been suggested to have a suppressive role in the progression of prostate cancer, highlighted by its downregulation in prostate cancer tissues and the fact that this was associated with higher Gleason scores." (PMID 33430066, 2021). "The other selected genes are HIST1H1E, LRAT, LCN2, KCNN4, RHOU, and EPHA5 in the order of them entering the model, among which LRAT, LCN2, RHOU, and EPHA5 are known to link to prostate cancer, and HIST1H1E and KCNN4 are connected to myeloma and pancreatic cancer, respectively." (PMID 29100492, 2017). "Interestingly, a recent transcriptomic analysis revealed that the EphA5 gene is downregulated in radical prostatectomy patients with high grade PCa with a Gleason score of 8,suggesting that EphA5 plays a crucial role in prostate cancer progression." (PMID 25609195, 2015). "Another fact that supports the importance of EphA5 in prostate cancer metastasis is that EphA5 transcript and protein levels were reduced consistently and significantly in both of the lymph node-derived cell lines compared with their parental prostate cancer cells (LNCaP and PC-3)." (PMID 25609195, 2015). "Here, we demonstrated that EphA5 is frequently downregulated in patients with prostate cancer." (PMID 25609195, 2015). "We found that EphA5 overexpression significantly decreased Du145 cell migratory and invasive capabilitie in vitro, suggestting that EphA5 may potentially suppress prostate cancer metastasis." (PMID 25609195, 2015). "Additionally, to elucidate the mechanisms leading to the downregulation of EphA5 expression in prostate cancer, we determined the relationship between transcript expression level and the methylation status of EphA5 in prostate cancer cell lines and tissues." (PMID 25609195, 2015). "As less is known about the mechanism of EphA5 downregulation and the function of EphA5, here we investigated the expression and an epigenetic change of EphA5 in prostate cancer and determined if these findings were correlated with clinicopathologic characteristics of prostate cancer." (PMID 25609195, 2015). "Our study provides evidence that EphA5 is a potential target for epigenetic silencing in primary prostate cancer and is a potentially valuable prognosis predictor and thereapeutic marker for prostate cancer." (PMID 25609195, 2015). "In addition, we also observed that EphA5 gene expression was decreased consistently and significantly in both lymph node derivative cell lines compared to their parental prostate cancer cells LNCaP and PC-3." (PMID 25609195, 2015). "Therefore, the detailed role of EphA5 in prostate cancer warrant further investigation." (PMID 25609195, 2015). "Therefore, EphA5 methylation might be useful as a marker for biological aggressiveness and as a valuable prognostic predictor of prostate cancer." (PMID 25609195, 2015). "Among the 23 paired prostate carcinoma specimens, 15 (65.2%) tumor tissues exhibited the downregulation of EphA5 when compared with their respectively matched noncancerous tissues." (PMID 25609195, 2015).
prostate carcinoma (continued). "Furthermore, the downregulation of EphA5 expression could be reversed in all 6 PCa cell lines by treating cells with the DNA demethylating agent 5-aza-2′-deoxycytidine, implying that hypermethylation was an important reason for promoting the downregulation of EphA5 expression in prostate cancer." (PMID 25609195, 2015). "To further verify the expression of EphA5 in human prostate tumors, we examined its expression via immunohistochemistry in 13 paired prostate carcinomas and noncancerous tissues." (PMID 25609195, 2015). "EphA5 mRNA expression was significantly decreased in all six prostate cancer cell lines compared to the nonmalignant RWPE-1 cells." (PMID 25609195, 2015). "However, the function of EphA5 and its clinical significance in prostate cancer has never been addressed." (PMID 25609195, 2015). "Of these 16 prostate cancer samples, 15(93.8%) exhibited the downregulation of EphA5 expression than that of their respectively matched noncancerous tissues, implying that the hypermethylation of EphA5 was significantly correlated with the downregulation of EphA5 (p < 0.01)." (PMID 25609195, 2015). "To explore the potential role of EphA5 in prostate carcinogenesis, we first analyzed its expression by real-time PCR in a panel of human nonmalignant (RWPE-1) and prostate cancer (LNCaP, LNCaP-LN3, PC-3, PC-3M-LN4, CWR22rv-1, and DU145) cell lines." (PMID 25609195, 2015).